GP9 (glycoprotein IX platelet)
Description:
The GPIb-V-IX complex functions as the vWF receptor and mediates vWF-dependent platelet adhesion to blood vessels. The adhesion of platelets to injured vascular surfaces in the arterial circulation is a critical initiating event in hemostasis. GP-IX may provide for membrane insertion and orientation of GP-Ib.
Synonyms: GPIX; CD42a
Tractability: Small molecule: a structure with a bound ligand is known. Antibody: its Gene Ontology location is reachable by antibodies, with high confidence; UniProt predicts a signal peptide or a membrane-spanning region; the Human Protein Atlas places it where antibodies can reach.
Gene: Protein-coding gene on chromosome 3 (129,060,779 to 129,062,435, forward strand). Ensembl gene ENSG00000169704.
Subcellular location: Membrane
Subcellular location (Human Protein Atlas): Cytosol; Plasma membrane; Nucleoplasm
Pathways (Reactome):
Hemostasis: Amplification and propagation of coagulation cascade; FXIIa, PKa-dependent activation of coagulation pathway; GP1b-IX-V activation signalling; Platelet Adhesion to exposed collagen; Platelet Aggregation (Plug Formation); Regulation of clotting cascade
Disease: Defective F9 activation; Defective binding of VWF variant to GPIb:IX:V; Enhanced binding of GP1BA variant to VWF multimer:collagen
Gene Ontology:
Molecular function: protein binding
Biological process: blood coagulation, intrinsic pathway; positive regulation of platelet activation; release of sequestered calcium ion into cytosol; blood coagulation; cell adhesion; megakaryocyte development
Cellular component: glycoprotein Ib-IX-V complex; plasma membrane; membrane
Genetic constraint (gnomAD): Missense variants: 228 observed, 229.79 expected, observed/expected ratio (o/e) 0.99, 90% interval 0.89 to 1.11. Synonymous variants: 116 observed, 109.12 expected, observed/expected ratio (o/e) 1.06, 90% interval 0.91 to 1.24.
Gene-disease validity (ClinGen):
ClinGen rates the evidence that GP9 causes each of these diseases.
Bernard-Soulier syndrome (autosomal recessive): Definitive. Bernard Soulier syndrome (BSS) is an inherited platelet disorder characterized by mild to severe bleeding tendency, macrothrombocytopenia and absent ristocetin-induced platelet agglutination.
Homologues: Orthologues: chimpanzee GP9 (98% identical), macaque GP9 (97% identical), dog GP9 (81% identical), guinea pig GP9 (74% identical), mouse Gp9 (71% identical), rat Gp9 (68% identical), rabbit GP9 (66% identical), pig GP9 (66% identical), tropical clawed frog GP9 (41% identical), zebrafish gp9 (30% identical). Paralogues in human: GP1BB (32% identical).
Diseases named in the same sentence as GP9 in open-access papers:
GP9 is named in the same sentence as 53 diseases in open-access papers, as found by Europe PMC text mining. Sharing a sentence is not in itself a finding about the gene and the disease. The quoted sentences say what the papers report.
Bernard-Soulier syndrome (8 papers, 2019 to 2025). "Variants in human GP9 are associated with Bernard-Soulier syndrome, type C. The deletion spanned 2460 bp, and included a significant part of the single coding exon of the canine GP9 gene on dog chromosome 20." (PMID 31484196, 2019). "Bernard-Soulier syndrome (BSS) is an autosomal-recessive bleeding disorder caused by biallelic variants in the GP1BA, GP1BB, and GP9 genes encoding the subunits GPIbα, GPIbβ, and GPIX of the GPIb-IX complex." (PMID 34638529, 2021). "Bernard-Soulier Syndrome: GP1BA, GP1BB, or GP9 genes cause a disorder of large platelets." (PMID 40822568, 2024). "Bernard-Soulier syndrome (BSS; MIM #231200) is a rare autosomal-recessive bleeding disorder caused by biallelic variants in the GP1BA, GP1BB, and GP9 genes that encode the subunits GPIbα, GPIbβ, and GPIX, respectively, of the GPIb-IX receptor complex." (PMID 34638529, 2021).
COVID-19 (5 papers, 2021 to 2022). A disease caused by infection with severe acute respiratory syndrome coronavirus 2. "Two of the shared-six genes between the McClain and Lee data were related to platelet function: glycoprotein IX platelet (GP9) and CKLF-like MARVEL transmembrane domain-containing protein 5 (CMTM5), both of which were consistently upregulated in a COVID-19 specific manner across the datasets." (PMID 35991542, 2022).
Macrothrombocytopenia (4 papers, 2006 to 2025). "Examples include: BSS (GP1BA, GP1BB, GP9 genes); platelet-type von Willebrand disease (GP1B1); GT (ITGA2B and ITGB3); MYH9-RD if there is macrothrombocytopenia, Döhle bodies, and/or typical extra hematologic manifestations (MYH9)." (PMID 40563486, 2025). "In contrast, macrothrombocytopenia, even with giant platelets, is typical of alterations in the GP1BA, GP1B, GP9, MYH9, SRC, and SLFN14 genes, and in the majority of ITs from variants in genes that encode cytoskeletal proteins or participate in glycosylation." (PMID 40563486, 2025).
Thrombocytopenia (4 papers, 2017 to 2023). A reduction in the number of circulating thrombocytes. "Recently, the International Mouse Phenotyping Consortium reported that the knockout of Gp9 in mice caused thrombocytopenia with increased platelet volume." (PMID 31484196, 2019). "Thus, mutations in the GP9 protein lead to a coagulation disorder, also known as the Bernard–Soulier syndrome, characterized by thrombocytopenia." (PMID 29387060, 2017).
Sepsis (3 papers, 2018 to 2025). Sepsis is defined as life-threatening organ dysfunction caused by a dysregulated host response to infection. "In addition, the combination of serum GP4 with other study measures (such as GP5 and GP9) in patients with sepsis significantly improved the prediction of the risk of death in the hospital." (PMID 40165956, 2025).
epilepsy (2 papers, 2022 to 2023). A brain disorder characterized by episodes of abnormally increased neuronal discharge resulting in transient episodes of sensory or motor neurological dysfunction, or psychic dysfunction. "In fact, GP9 has already been associated with neural-dysregulation and neurotoxicity, as aberrant expression of this gene has been measured in blood cells of Epilepsy and Multiple Sclerosis patients." (PMID 36694130, 2023).
bleeding disorder (1 paper, 2014). "Bernard–Soulier syndrome (BSS) is an extremely rare (1: 1,000,000) bleeding disorder of platelet adhesion, caused by defects in the glycoprotein genes GP1BA (encoding GPIbα), GP1BB (encoding GPIbβ) and GP9 (GPIX) with autosomal recessive inheritance pattern." (PMID 25275492, 2014).
dementia (1 paper, 2021). Loss of intellectual abilities interfering with an individual's social and occupational functions. "Diagnostic model including GP8, GP9, and GP14 was of promising capability to distinguish dementia from NC group with an AUC of 0.876 (95% CI: 0.815–0.923) and distinguish AD from NC group with an AUC of 0.887 (95% CI: 0.819–0.936) under 5-fold cross-validation random forest classifiers." (PMID 33542243, 2021). "The AUC value of the model including GP8, GP9, and GP14 was determined to distinguish dementia from NC groups as 0.876 (95% confidence interval [CI]: 0.815–0.923)." (PMID 33542243, 2021). "The area under the receiver operating curve (AUC) value of the model consisting of GP8, GP9, and GP14 was determined to distinguish dementia from NC group as 0.876 [95% confidence interval (CI): 0.815–0.923] and distinguish AD from NC group as 0.887 (95% CI: 0.819–0.936)." (PMID 33542243, 2021). "GP8, GP9, and GP14 were selected by intersection of dimension reduction methods [the Ridge and Stepwise (including the direction of Forward and Backward) based on logistic regression as well as Lasso regression], and thus were identified as a biomarker panel for the diagnosis of dementia." (PMID 33542243, 2021). "In addition, 7 initial glycans (increased relative abundance of GP8, GP9, GP12, GP21, and GP23 as well as reduced relative abundance of GP16 and GP18) were of significant differences between dementia and MCI groups after adjusting these confounders (p < 0.05; q < 0.05)." (PMID 33542243, 2021).
Ebola (1 paper, 2017). "Previous results had demonstrated that NPC1 mediates the entry of Ebola, and some small molecular inhibitors block the infection of Ebola by disturbing the interactions between NPC1 domain C and Ebola primed GP9." (PMID 28117364, 2017).
gram-positive bacterial infections (1 paper, 2025). Infections caused by bacteria that retain the crystal violet stain (positive) when treated by the gram-staining method. "Combination therapy (GP5, GP9) effectively normalized these parameters, closely approximating those of the uninfected control group (GP1), and highlighting its therapeutic potential in managing both Gram-negative and Gram-positive bacterial infections." (PMID 40672366, 2025).
post-traumatic stress disorder (1 paper, 2020). An anxiety disorder precipitated by an experience of intense fear or horror while exposed to a traumatic (especially life-threatening) event. "Another module downregulated in the early adversity group was related to platelet activation and wound healing (hub genes: GP9, CMTM5, TUBB1, GNG11, PF4), and resembled a co-expression module previously found over-expressed in post-traumatic stress disorder resilient soldiers." (PMID 32066736, 2020).
prediabetes (1 paper, 2023). "After adjusting for age, sex, BMI, and family, 2 glycans, GP9 and GP11, were negatively associated with prediabetes, and GP32 was positively associated (step 2)." (PMID 37400796, 2023). "Additionally, 3 of the postprandial triglyceride–associated glycans (GP9, GP11, and GP32) also correlate with prediabetes and partially mediate the relationship between prediabetes and postprandial triglycerides." (PMID 37400796, 2023).
cancer (5 papers, 2018 to 2023). A tumor composed of atypical neoplastic, often pleomorphic cells that invade other tissues. "Segregation analysis based on these groups (GP8, GP9, GP14, GP23, and coreF) revealed a significant separation between normal and cancer MDG serum samples and showed a significant correlation in matched serum." (PMID 29698574, 2018).
infection (4 papers, 2012 to 2024). The state of being infected such as from the introduction of a foreign agent such as serum, vaccine, antigenic substance or organism. "Expression of SiOBP3/gp9 gradually decreased during B. bassiana infection and was at ∼50% 72 h post-infection." (PMID 33746766, 2021).
cardiovascular disease (1 paper, 2025). "In addition, high levels of GP7 correlated with death from cardiovascular disease, whereas high levels of GP9 correlated with protection against it." (PMID 41106480, 2025).
GP9 also shares sentences with these, for which no sentence is quoted: Hypertension (3 papers); diabetes (2); Glanzmann thrombasthenia (2); ischemic stroke (2); systemic lupus erythematosus (2); thrombosis (2); acute myeloid leukaemia (1); amyotrophic lateral sclerosis (1); Anxiety (1); Autoimmunity (1); cardiac disease (1); chronic heart failure (1); coagulation disorder (1); coronary artery disease (1); Down syndrome (1); dyslipidemia (1); hemophilia A (1); Insulin resistance (1); iron-refractory iron deficiency anemia (1); lymphoid leukemia (1); malaria (1); megakaryoblastic leukemias (1); melanoma (1); multiple sclerosis (1); myocardial infarction (1); neuroblastoma (1); Obesity (1); osteoporosis (1); pemphigus (1); platelet disorders (1).
A further 8 diseases each share a sentence with GP9 in 1 paper.